MCU (mitochondrial calcium uniporter)
Diseases named in the same sentence as MCU in open-access papers (continued):
Sharing a sentence is not in itself a finding about the gene and the disease.
tumor (37 papers, 2016 to 2025). "In this study, we show that MCU is overexpressed in ERMS tumours and its silencing causes a reduction in mitochondrial Ca2+ uptake." (PMID 35490194, 2022). "Mitochondrial ion channels such as the mitochondrial calcium uniporter (MCU) are critical for tumour growth, influencing cell cycle progression and energy metabolism essential for CSC maintenance." (PMID 40806720, 2025). "In colorectal cancer (CRC), MCU expression is significantly increased, promoting mitochondrial biogenesis and enhancing tumor growth." (PMID 40724998, 2025). "We analyzed the TCGA-STAD cohort data at the cellular level to investigate the relationship between MCU expression and immune cells in the tumor microenvironment." (PMID 38737905, 2024). "MCU expression was notably concentrated in the tumor areas across all 15 clusters, exhibiting highly significant differences in expression, second only to TBFb1." (PMID 38632642, 2024). "As scientific research continues to advance, it has been found that the role of MCU and its regulators in tumour is becoming increasingly clear." (PMID 38356708, 2024). "It is believed that the expression of MCU is related to tumour size and lymphatic infiltration, which suggests that it supports tumour growth and metastasis." (PMID 38356708, 2024). "As tumor mutation burden (TMB) was a robust prognostic indicator in COAD, we analyzed the relationship between the expressions of MCU complex members and TMB in COAD." (PMID 37056383, 2023). "Here, we explored the mechanism by which MCU regulates BC cell migration from the perspective of tumor cell autophagy." (PMID 37885995, 2023). "As metastasis is a key factor that contributes to tumor progression, it is necessary to determine the role of MCU in mediating the migration ability of BC cells." (PMID 37885995, 2023). "Genetic deletion of MCU dramatically reduced tumor burden in vivo, due to a strong reduction in the proliferative capacity of cells in vivo and in vitro, particularly under conditions of nutrient stress." (PMID 37363724, 2023). "Deletion of MCU strongly delayed tumor growth in vivo and decreased cell proliferation in vitro and in vivo." (PMID 37363724, 2023). "Previous studies have indicated that MCU regulates tumor growth and invasiveness through multiple mechanisms." (PMID 37885995, 2023). "Genetic deletion of MCU delayed tumor growth primarily by decreasing cell proliferation that resulted in a smaller tumor size, lower Ki-67 index and reduced number of mitotic cells." (PMID 37363724, 2023). "MCU expression was also examined in six archival ERMS tumour sections by immunohistochemistry (IHC) using anti-MCU antibody." (PMID 35490194, 2022). "Mitochondrial calcium uniporter (MCU) can promote tumor metastasis by activating the Keap1–Nrf2–SLC7A11 axis." (PMID 36552652, 2022). "Here, we show that ERMS cell lines as well as primary tumours exhibit elevated expression of the mitochondrial calcium uniporter (MCU)." (PMID 35490194, 2022). "Specifically, miR-340 targets the UTR of mitochondrial calcium uniporter (MCU) gene and represses the expression to reduce tumor growth and metastasis." (PMID 33824695, 2021). "It has been reported that the promoters of other members can be recognized by CREB, and once bound to the promoter, the tumor highly expresses MCU, MICU1, and MICU2." (PMID 33114428, 2020). "Inasmuch as the MCU is a Ca2+-activated, Ca2+ channel, high Ca2+ domains in tumor cells should lead to more efficient mitochondrial Ca2+ uptake followed by prevention of the ensuing slow, Ca2+-dependent inactivation of SOCs." (PMID 28903423, 2017). "In 41 tumor-specific SEs, several SEs with significant H3K27ac enrichment were close to previously reported tumor-related genes, like MCU, MPRIP and PSAP (Supplementary-2)." (PMID 29285248, 2017). "Expression of MCU and its modulatory protein MICU1 are similar in normal and tumor cells at the mRNA level, being mRNA for MCU much more abundant than for MICU1." (PMID 28903423, 2017).
tumor (continued). "A number of proteins contribute to the channel complex and others regulate its activity, but little is known about the role of MCU‐dependent mitochondrial Ca2+ homeostasis in tumor progression." (PMID 27138568, 2016). "Accordingly, MCU downregulation hampered cell motility and invasiveness and reduced tumor growth, lymph node infiltration, and lung metastasis in TNBC xenografts." (PMID 27138568, 2016). "Our results revealed that the expression of MCU, the highly selective channel responsible for mitochondrial Ca2+ uptake, correlates with tumor progression." (PMID 27138568, 2016). "NCOA4 overexpression reverses these effects, reducing MCU expression and tumor growth." (PMID 41041538, 2025). "Comparing Mitochondrial Calcium Uniporter (MCU) with other genes associated with T cell regulation, MCU exhibited higher expression levels in tumor areas compared to non-tumor areas." (PMID 38632642, 2024). "After the expression of MCU was found to be negatively correlated with BC patient prognosis from the Kaplan‒Meier plotter database, we performed our research with clinical samples to determine the biological role of MCU in the tumor progression of BC." (PMID 37885995, 2023). "To further understand the mechanism by which deletion of MCU impedes tumor growth, we performed histological analyses of tumors, examining characteristics associated with tumor growth patterns, including amount of normal and necrotic tumor tissue and mitotic activity." (PMID 37363724, 2023). "Overexpression of MCU activates autophagy to promote tumor cell migration." (PMID 37885995, 2023). "Now, MCU complex members were considered as potential therapeutic targets for malignancies treatment, and the agonists or antagonists presented well potential anti-tumor activity in the preclinical assays and clinical trials." (PMID 37056383, 2023). "Therefore, unsurprisingly, some mitochondrial calcium transporters, such as the MCU, have recently been found to be involved in autophagy and mitophagy regulation in tumor cells." (PMID 35743109, 2022). "Moreover, a significant reduction in p-SMAD3 levels was seen in MCU knockdown tumours by western blot analysis." (PMID 35490194, 2022). "However, in MDA-MB-231 breast carcinoma, MCU downregulation reduced tumor growth and metastasis, implying that mitochondrial Ca2+ uptake enhanced tumorigenesis of some cancers." (PMID 32039198, 2019). "Indeed, several compounds with anti-tumor activity act by promoting mitochondrial calcium overload and consequently cell death, which can be inhibited by MCU blockers." (PMID 32039198, 2019). "Moreover, silencing MCU in TNBC cells strikingly inhibited in vivo tumor growth and metastasis progression in mice." (PMID 28495532, 2018). "Bioinformatic analysis corroborated this hypothesis indicating a relatively small but strongly significant increase in the expression of the channel forming subunit of the MCU complex during tumor progression." (PMID 27138568, 2016). "Because mitochondria can play an important role in buffering changes of [Ca2+]cyt, and alterations in [Ca2+]cyt may regulate cell-biological functions of tumor cells, we also examined InsP3R-mediated Ca2+ signaling in transformed fibroblasts and two clones with MCU deleted." (PMID 37363724, 2023). "In essence, our study enriches the understanding of MCU's role in BRCA, drawing insights from clinical tumor samples and paving the way for the development of innovative immunotherapy strategies." (PMID 38632642, 2024). "The tumor cell lines showed significantly higher expression of MCU and MICU1 than the non-tumor cell line." (PMID 39466877, 2024). "Using western blotting, we compared the protein expression of MCU, MICU1, and MICU2 in a non-tumor colorectal epithelial cell line, NCM356, and in 5 CRC cell lines (HT29, DLD1, SW480, HCT116, and SW620) with different mutation and aggressiveness profiles." (PMID 39466877, 2024).
tumor (continued). "MCU knockdown inhibits HIF-1α expression, thereby attenuating the transcription of HIF-1α involved in tumor progression." (PMID 32152662, 2020). "MCU was silenced in three TNBC cell lines, which strikingly inhibited cell migration, in vivo tumor growth and metastasis progression." (PMID 28495532, 2018). "Interestingly, even in the presence of activated CREB, there is an increase in the levels of MCU, MICU1, and MICU2 that significantly enhances tumor growth." (PMID 33114428, 2020). "Moreover, MCU silencing downregulates HIF‐1α expression, thus impairing the transcription of HIF‐1α‐target genes involved in tumor progression." (PMID 27138568, 2016). "In particular, while MCU expression increases with tumor progression, the expression of MCUb, the dominant‐negative channel isoform, decreases." (PMID 27138568, 2016). "As the infiltration of immune cells in tumor microenvironment (TME) was closely related to the prognosis and responses to immunotherapy in COAD, we then analyzed the relationship between the expressions of MCU complex members and the distribution of immune cell infiltration in COAD." (PMID 37056383, 2023). "This study includes tumor specimens and adjacent normal liver tissue from 354 patients with confirmed HCC as study subjects and concluded that HCC patients with low MICU1 and high MCU/MICU2 expression exhibited poor survival rates, overall survival rates and disease-free survival rates." (PMID 35743109, 2022). "We found that MCU depletion partially rescued STING depletion‐induced cell growth inhibition in vitro, which correlated with reduced mitochondrial ROS, suggesting that mitochondrial ROS/calcium increases may partially explain observed cell growth inhibition in STING‐depleted tumor cells." (PMID 36445063, 2023). "However, whether MCU-dependent mito-metabolism counteracts cell death signaling in tumor cells has not been reported." (PMID 37502961, 2023). "Furthermore, by LSCM, an increase in TFEB nuclear translocation was clearly observed after MCU was activated, whereas the opposite change was detected in MCU-inhibited cells, suggesting that MCU could activate TFEB-driven autophagy to promote tumor cell migration." (PMID 37885995, 2023).
infection (7 papers, 2017 to 2025). The state of being infected such as from the introduction of a foreign agent such as serum, vaccine, antigenic substance or organism. "RIPK3-initiated necroptosis is crucial for host defense against Streptococcus pneumoniae, forming complexes with RIPK1, MLKL, and MCU (mitochondrial calcium uniporter) during infection to induce mitochondrial calcium uptake and mROS production." (PMID 38257794, 2024). "It was demonstrated that MCU expression rises upon the infection, and MCU dependent increased mitochondrial Ca2+ uptake activates the NLRP3 complex, causing mitochondrial dysfunction such as increased ROS generation and apoptosis." (PMID 32327997, 2020). "During an infection with Scutellaria pneumoniae, MLKL interacts with RIPK1, RIPK3, and MCU (mitochondrial calcium uniporter) to induce mitochondrial calcium uptake and the production of mROS." (PMID 40070567, 2025).
cardiovascular disease (5 papers, 2019 to 2025). "This represents a significant methodological advancement, establishing for the first time a causal relationship between genetically predicted SMDT1-encoded MCU regulator levels and various cardiovascular diseases." (PMID 40422231, 2025). "However, the potential involvement of genetic polymorphisms in MCU complex genes in the context of cardiovascular disease, particularly SCD-CAD, remains largely unexplored." (PMID 40422231, 2025). "In cardiovascular disorders, reduced MCU expression contributes to Ca2+ dysregulation, whereas MCU overexpression has been found to exert protective effects by enhancing cardiovascular cell function." (PMID 40429873, 2025). "Mitochondrial calcium uniporter (MCU) complex activation and mitochondrial calcium ([Ca2+]m) overload are underlying mechanisms involved in cardiovascular disease." (PMID 34914018, 2021). "However, the role of upregulating or downregulating MCU complex activity in the progression of cardiovascular diseases remains controversial." (PMID 40422231, 2025). "In cardiovascular diseases, inhibition of CypD blocked the activation of mPTP in isolated mitochondria, thereby reducing cell death during ischemia-reperfusion injury in the heart.This study investigated the expression of MCU and CypD in vivo and in vitro, respectively." (PMID 40799639, 2025).
neurodegenerative disease (5 papers, 2015 to 2025). A disorder of the central nervous system characterized by gradual and progressive loss of neural tissue and neurologic function. "Indeed several recent review articles have suggested that targeting the MCU complex could be a potential therapeutic target for treating neurodegenerative diseases." (PMID 33271784, 2020). "Calcium uptake via the mitochondrial calcium uniporter (MCU) complex and mitochondrial calcium overload play a key role in neurodegenerative diseases, including DLB35,36." (PMID 34686734, 2021). "Additionally, MCU and MICU1 expression levels are negatively correlated with age, potentially explaining the increased incidence of neurodegenerative diseases with aging." (PMID 40003583, 2025). "We previously found that RSL3-induced oxytosis/ferroptosis led to the upregulation of the mitochondrial calcium uniporter (MCU), a protein described to be involved in the early pathophysiology of neurodegenerative diseases due to its role in the Ca2+-dependent membrane potential and bioenergetics." (PMID 38671908, 2024).
metabolic disease (3 papers, 2018 to 2024). A congenital disorder (due to inherited enzyme abnormality) or acquired (due to failure of a metabolically important organ) disorder resulting from an abnormal metabolic process. "Therefore, our data indicates that MCU plays contributes to the development or progression of a wide variety of diseases including metabolism disorders by altering or controlling its expression and activity." (PMID 39523398, 2024).
myopathy (3 papers, 2018 to 2020). A disease of the muscle in which the muscle fibers do not function properly. "Of note, muscle biopsies also showed up-regulation of members of the mitochondrial Ca2+ uptake machinery (MCU, MCUR1), indicating that increased mitochondrial Ca2+ uptake might also happen in vivo, as part of the pathological process in core myopathies." (PMID 29701772, 2018).
neurological disorders (3 papers, 2018 to 2021). "Previous studies have suggested that the cellular Ca2+ and iron homeostasis, which can be regulated by mitochondrial calcium uniporter (MCU), is associated with oxidative stress, apoptosis and many neurological diseases." (PMID 30756474, 2019).
MCU also shares sentences with these, for which no sentence is quoted: glioblastoma (3 papers); age (1); Alzheimer disease (1); Anxiety (1); bladder cancer (1); Burkitt lymphoma (1); cardiac arrhythmias (1); cardiac diseases (1); cervical cancer (1); chronic pancreatitis (1); COVID-19 (1); deafness (1); diabetic cardiomyopathy (1); Diabetic Nephropathy (1); extrapyramidal movement disorder (1); Huntington disease (1); hypertrophy (1); infarction (1); injury (1); learning disability (1); liver diseases (1); lymph node metastasis (1); metastatic tumors (1); pancreatitis (1); status epilepticus (1); type 1 diabetes (1).